CDKN2A (cyclin dependent kinase inhibitor 2A)
Diseases named in the same sentence as CDKN2A in open-access papers (continued):
Sharing a sentence is not in itself a finding about the gene and the disease.
cancer (continued). "However, only CDKN2A status remained significant (HR: 1.72, 95% CI: 1.34–2.21, p < 0.001) after adjusting for age at metastatic diagnosis, gender, and cancer type in the multivariate Cox regression models." (PMID 34204917, 2021). "Indeed, using cancer cell lines to confirm the TYMS dependency predicted by PARIS, we discovered that the most robust effects can be observed in those lines where TYMP is expressed at high levels and CDKN2A is mutated or deleted." (PMID 34454516, 2021). "Whether CDKN2A SCND drives human cancer metastasis is far from clear." (PMID 35004325, 2021). "Recent surveys of cancer genome landscapes have shown that alterations of a particular pathway can involve many different genes and many different kinds of disruptions—for example, RB1 mutation, RB1 methylation, or CDKN2A deletion can all lead to aberrant cell proliferation." (PMID 33861732, 2021). "Abnormal expression of CDKN2A may be related to the occurrence of many cancers." (PMID 35004697, 2021). "Although one of the most common genetic alterations in human cancer is the deletion of the Cdkn2a/b gene locus encoding for the cell cycle regulators p15Ink4b, p16Ink4a and ARF-Ink4a, it seems that these factors do not play a major role in EC development and physiology." (PMID 33078209, 2021). "ICB did not attenuate the growth of Cdkn2a-deficient RT2-cancers." (PMID 32165639, 2020). "Importantly, CDKN2A mutation carriers have been reported to be at increased risk of developing other cancers, including breast, lung, and non-melanoma skin cancers." (PMID 33076392, 2020). "Finally, CNAtra successfully detected the previously-reported focal amplifications of MYC (NCI-H82) and MYCN (CHP-212, IMR-32) loci as well as homozygous focal deletions of BANK1/4q24 (NCI-H82), LKB1/STK11 (A427), and p16INK4a/CDKN2A (A427) loci in respective cancer cell lines." (PMID 32299346, 2020). "Using DNA copy number copy number data from 9744 cancer specimens belonging to 39 cancer subtypes, we show that linear deletion limitation exists, and exploit it to expose deletion-limiting genes for seven deletion targets (CDKN2A, RB1, PTEN, MAP2K4, NF1, SMAD4, and LINC00290)." (PMID 31341961, 2019).
cancer (continued). "MPM exhibits a distinct genomic signature, including inactivating mutations in cyclin-dependent kinase inhibitor 2A (CDKN2A), and more recently, ubiquitin carboxyl-terminal hydrolase (BAP1) and neurofibromin 2 (NF2), have been shown to be the most prevalent in this type of cancer." (PMID 29342862, 2018). "However, the cancer driver genes located on it remain largely unknown, except the tumor suppressor gene, p16 (INK4)/CDKN2A." (PMID 29805750, 2018). "Moreover, several studies showed that mir-31 and CDKN2A are concurrently deleted in cancers." (PMID 30501131, 2018). "Interestingly, these two candidate driver lncRNAs RP11‐571M6.8 and NKX2‐1‐AS1 were mutually exclusive with a common gene CDKN2A with frequent genetic alterations (> 10%) in GBM and LUAD, respectively, affecting the same cancer hallmark ‘Insensitivity to Antigrowth Signals’." (PMID 30216655, 2018). "Increasing evidence demonstrates that methylation of the promoter of CDKN2A, an important negative regulator of cell growth and proliferation, is involved in the tumorigenesis and progression of various tumors, including pancreatic, gastric, and prostate cancers." (PMID 28637022, 2017). "As the numbers were very small for families with FPC, the benefit of their surveillance is still unknown and equally the growth pattern differences between CDKN2A mutated and FPC cancers is unknown, so the effect that this could have on surveillance strategies remains to be seen." (PMID 29069866, 2017). "With CDKN2A, on the other hand, there is no known gender difference with regard to cancer risk." (PMID 27804060, 2017). "We show that hypermethylation of p16/Ink4a and p19/Arf in CNT- and asbestos-induced inflammatory lesions precedes mesothelioma; this results in silencing of Cdkn2a (Ink4a/Arf) and loss of p16 and p19 protein, consistent with epigenetic alterations playing a gatekeeper role in cancer." (PMID 29112861, 2017). "Additionally, the 9p21.3 region, that includes in addition to CDKN2A also CDKN2B and CDKN2B-AS1, is pleiotropic and several polymorphic variants in the region spanning the three genes are susceptibility markers for several cancer types." (PMID 27486979, 2016). "In C. albicans-induced chronic inflammation-associated cancer, it is probable that p16 protein overexpression might be caused by alternative pathways such as CDKN2A gene mutation or loss of the Rb gene irrespective of p16 promoter hypermethylation." (PMID 27410681, 2016). "Despite the fact that several patients had aberrations in some genes such as CTTNB1 and CDKN2A, the specific combination of aberrations and their subtypes were unique to each individual patient, important distinctions for selecting personalized cancer therapies." (PMID 24931142, 2014). "Furthermore, we showed that the induced RCCs have massive chromosomal alterations similar to those of human cancers, of which the amplification of c-Met (receptor for hepatocyte growth factor) and deletion of Cdkn2a/2b (p16Ink4a/p15Ink4b tumor suppressor genes) are most common." (PMID 25221514, 2014). "Moreover, co-deletion of PTPRD and CDKN2A occurs across a number of cancer types." (PMID 25138050, 2014). "Importantly, CDKN2A encoding p16 is localised to the most commonly affected 9p21-22 locus, which shows LOH in 46–71% of premalignant lesions and 72% of carcinoma and is strongly associated with progression to cancer and metastasis." (PMID 24364026, 2013).
cancer (continued). "Thus, the frequent occurrence of chromosome 8/15 gains together with specific losses at the Cdkn2a locus might represent early events occurring in cancer pre-stages and promoting malignant transformation." (PMID 21533183, 2011). "However, it should be noted that some cancer cell line data suggests that CDKN2A exon 2 DNA methylation is not necessarily associated with gene silencing." (PMID 21731750, 2011). "Inhibiting DNA methyltransferases can lead to increased methylation in the CpG-rich promoter regions of cyclin-dependent kinase inhibitor A (CDKN2A), inducing the expression of INK4A and ARF, which results in cancer cell senescence." (PMID 40149983, 2025). "For instance, a study reported that the DNA hypermethylation of three cancer-related genes (MTHFR, RASSF1A, and CDKN2A) is influenced by tobacco smoking level or gender in lung cancer patients." (PMID 40332491, 2025). "While CDKN2A is a well-established tumor suppressor gene, the role of MTAP in tumorigenesis varies across cancer types." (PMID 41439984, 2025). "Homozygous deletion of the 9p21.3 genomic locus spanning the CDKN2A/B and MTAP genes is an event affecting 15% of cancers." (PMID 41439984, 2025). "CDKN2A was significantly upregulated, while LCK, key gene in the maintenance of the undifferentiated state, was significantly downregulated in MSCs vs. cancer cells and iPSC lines." (PMID 39621192, 2025). "MTAP is frequently deleted in various cancers, including TNBC, often as a codeletion event with cyclin-dependent kinase inhibitor 2A (CDKN2A)." (PMID 40590221, 2025). "Several known cancer and human MM driver genes were observed within focal GISTIC peaks, including homozygous deletions of Cdkn2a/b (7.3%), Rb1 (7.3%), and Pten (4%)." (PMID 38714690, 2024). "These cells are homozygous null mutants for the CDKN2A locus, which makes them a good model to study the CDKN2A-independent function of EZH2 in cancer." (PMID 39174513, 2024). "Significantly, a meta-analysis confirmed the positive correlation between CDKN2A ALT, CDKN2A MUT, CDKN2A DEL, and unfavorable prognosis in pan-cancers." (PMID 38822443, 2024). "Based on this, we found that CDKN2A-ALT has a poor prognostic effect in some tumors, so pan-cancer analysis was subsequently performed." (PMID 38822443, 2024). "We explored the prevalence of CDKN2A ALT among 10,194 patients across 25 cancer types in the OrigiMed 2022 cohort with clinical data." (PMID 38822443, 2024). "In Cuproptosis-related genes, SPC25 was positively correlated with GCSH, CDKN2A, PDHB, PDHA1, DLAT, DLD, and SLC31A1 of pan-cancer." (PMID 38605119, 2024). "Recently, we discovered that SIRT7 destabilizes the cyclin dependent kinase inhibitor 2A (CDKN2A, known as ARF) within the nucleolus, aiding cancer progression." (PMID 39036727, 2024). "Hypermethylation of cancer suppressor genes such as RB1, CDKN2A, MLH1, VHL, and BRCA1, leading to their repression, has been observed in various cancer types." (PMID 38970307, 2024).
cancer (continued). "Combined with high expression of CDKN2A and subsequent upregulation of the host cell cycle and proliferation-related genes in HOP-HPV-positive biopsies, this could be a hallmark for the transformation of a transient to persistent HPV infection and an important step towards the development of cancer." (PMID 39712018, 2024). "Functional protein association network analysis of the gene frequently mutated in the recurrent tumors showed enrichment of genes that regulate the cancer cell cycle, that is, MRE11A, CDKN2A, and CYLD." (PMID 38477073, 2024). "A total of 6 CRSGs were screened out, including CDKN2A, GLS, FDX1, PDHA1, PDHB, and DLD; most of them have been reported in the direct regulation of cuproptosis and cancer progression." (PMID 37287976, 2023). "From the functional annotation analysis, CDKN2A, VEGFA, PTGS2, and STAT1 were involved in cancer pathways (hsa05200; KEGG pathway)." (PMID 36765810, 2023). "When K = 2, each detected gene set, except for (CDKN2A, CYP27B1) identified by method iMCMC, is enriched in one cancer-related biological pathway." (PMID 37221474, 2023). "After NF1 loss, nearly all ANNUBPs are characterized by the deletion or silencing of the INK4a/ARF (originally called CDKN2A) tumor suppressor locus, which is inactivated in the majority of human cancers." (PMID 37686402, 2023). "In cancer cells, the MTAP gene is frequently co-deleted with CDKN2A, and this results in MTA-mediated inhibition of the methyltransferase PRMT5; in line with this, the sensitivity to PRMT5 inhibitors is higher in cells with increased MTA levels." (PMID 37563469, 2023). "Among these potential druggable alterations, EGFR, KRAS, and PIK3CA gene alterations were the most common, while CDK pathway (CDK4/6, CDKN2A/2B), FGFR1/2/3, BRAF, RET was uncommon across pan-cancer." (PMID 36910668, 2023). "A number of pivotal cancer-related genes, including HER2, CCND1, PIK3CA, and CDKN2A, were pinpointed within the top 500 genes in both the differential signaling network and the analysis of differentially expressed genes." (PMID 38087279, 2023). "Cyclin dependent kinase inhibitor 2A (CDKN2A), also known as P16, is a tumor suppressor gene that can induce cancer cell senescence." (PMID 37723477, 2023).
cancer (continued). "The results of this study showed that compared with normal tissues, the expression of CDKN2A and ZBP1 in cancer cells was significantly increased, while the expression of MYCN was on the contrary." (PMID 37878133, 2023). "The 9p21.3 region, which contains the three tumor suppressor genes CDKN2A, CDKN2B and MTAP, is known to be frequently deleted in different types of cancer cells." (PMID 36762651, 2023). "We further show that this germ cell–like transcriptional program, even when reduced to the top two genes (CDKN2A and SYCP2), serves as a fingerprint of oncogenic HPVs with implications for early detection, diagnosis, and therapy of all HPV-driven cancers." (PMID 36213965, 2023). "One possible mechanism is that CDKN2A inhibits cell in cell (CIC) structures to limit the crosstalk between the multiple signals of each and thus decreases cancer cell death." (PMID 36895378, 2023). "ASPH, CDKN2A, E2F1, P3H1, and PTTG1 were identified as prognostic indicators of unfavorable outcomes within multiple cancer types." (PMID 37497116, 2023). "We uncovered that CDKN2A was positively correlated with infiltration degree of CD4+ T cells, NKT cells, Tregs, MDSC, neutrophils and macrophages in most TCGA cancers." (PMID 36961395, 2023). "Furthermore, we present unexpected predictive models of several DDR deficiencies; ATRX and IDH1 deficiency in cancers of the central nervous systems (CNSs), HERC2 and CDKN2A deficiency in skin, PTEN deficiency in cancers of the CNS and uterus, and SMARCA4 deficiency in cancers of unknown primary." (PMID 36883553, 2023). "Other high-penetrant cancer genes BRCA1, APC, STK11 and moderate-penetrant genes BRIP1, CDKN2A, FANCI and MET had a similar frequency 1 (5.8%)." (PMID 37277882, 2023). "The cell types more abundant in LUSC (SOX2, CDKN2A, proliferating cancer) were placed later in pseudotime than the LUAD-specific cell types (alveolar, pathological alveolar, CXCL1 cancer)." (PMID 36973297, 2023). "Starting from alveolar cells, the cells transformed into pathological alveolar cells, CXCL1, LAMC2, CDKN2A, proliferating, and SOX2 cancer cells as they progressed in pseudotime." (PMID 36973297, 2023). "Then we conducted pan-cancer survival analysis of CDKN2A and we found that the OS, DSS, DFS, PFS time of the CDKN2A altered group are all shorter than unaltered group (all the four p-value <0.001, log-rank test)." (PMID 36961395, 2023). "In contrast to LUAD, LUSC samples were more abundant in CDKN2A (14.65% vs 1.05%), proliferating (26.33% vs 1.73%), and SOX2 cancer cells (43.89% vs 24.18%)." (PMID 36973297, 2023). "The differential expression analyses of OSCC tissues and para-cancer tissues demonstrated that LIAS and PDHB were suppressed in cancer tissues, but GLS and CDKN2A were accelerated." (PMID 35875097, 2022).